APOH (apolipoprotein H)
Description:
Binds to various kinds of negatively charged substances such as heparin, phospholipids, and dextran sulfate. May prevent activation of the intrinsic blood coagulation cascade by binding to phospholipids on the surface of damaged cells.
Synonyms: B2G1; BG; B2GP1
Tractability: Small molecule: it has a binding pocket of medium quality. Antibody: its Gene Ontology location is reachable by antibodies, with high confidence; UniProt places it where antibodies can reach, with medium confidence; UniProt predicts a signal peptide or a membrane-spanning region. PROTAC: its protein half-life has been measured.
Gene: Protein-coding gene on chromosome 17 (66,211,595 to 66,256,525, reverse strand). Ensembl gene ENSG00000091583.
Subcellular location: Secreted
Subcellular location (Human Protein Atlas): Golgi apparatus; Predicted to be secreted
Pathways (Reactome):
Hemostasis: Platelet degranulation
Gene Ontology:
Molecular function: identical protein binding; lipase binding; lipid binding; lipoprotein lipase activator activity; phospholipid binding; protein binding
Biological process: blood coagulation, intrinsic pathway; chylomicron remodeling; negative regulation of angiogenesis; negative regulation of blood coagulation; negative regulation of endothelial cell migration; negative regulation of endothelial cell proliferation; negative regulation of fibrinolysis; negative regulation of myeloid cell apoptotic process; negative regulation of smooth muscle cell apoptotic process; plasminogen activation; positive regulation of triglyceride metabolic process; regulation of fibrinolysis; triglyceride transport; very-low-density lipoprotein particle remodeling; positive regulation of blood coagulation
Cellular component: cell surface; chylomicron; extracellular exosome; extracellular region; Golgi apparatus; high-density lipoprotein particle; very-low-density lipoprotein particle; platelet dense granule lumen
Genetic constraint (gnomAD): Loss-of-function variants: 47 observed, 38.85 expected, observed/expected ratio (o/e) 1.21, 90% interval 0.96 to 1.54. The upper end of that interval is the gene's LOEUF score, 1.54, which puts it in group 6 of 6, group 1 being the genes least tolerant of losing a copy. Missense variants: 405 observed, 435.1 expected, observed/expected ratio (o/e) 0.93, 90% interval 0.86 to 1.01. Synonymous variants: 151 observed, 158.51 expected, observed/expected ratio (o/e) 0.95, 90% interval 0.83 to 1.09.
Homologues: Orthologues: chimpanzee APOH (99% identical), macaque APOH (95% identical), pig APOH (83% identical), rat Apoh (82% identical), dog APOH (82% identical), mouse Apoh (77% identical), guinea pig APOH (56% identical), tropical clawed frog apoh (40% identical). Paralogues in human: CSMD1 (23% identical), CSMD3 (23% identical), CFH (22% identical), CSMD2 (22% identical), CR2 (21% identical), C4BPA (21% identical), CR1 (21% identical), SEZ6 (21% identical), SVEP1 (20% identical), SEZ6L2 (19% identical), CR1L (18% identical), SEZ6L (18% identical), and 27 more.
Diseases named in the same sentence as APOH in open-access papers:
APOH is named in the same sentence as 206 diseases in open-access papers, as found by Europe PMC text mining. Sharing a sentence is not in itself a finding about the gene and the disease. The quoted sentences say what the papers report.
antiphospholipid syndrome (108 papers, 2003 to 2026). A disorder caused by the presence of autoantibodies directed against phospholipids, causing a hypercoaguable state, which may result in blood clots, stroke, heart attack, and in women, significant pregnancy-related complications, including miscarriage and still birth. "While ApoH antibodies are primarily associated with antiphospholipid syndrome and lupus anticoagulant, where they promote thrombosis, recent studies suggest a broader role beyond coagulation." (PMID 40137160, 2025). "APOH, a key antigen in antiphospholipid syndrome (APS), highlights a possible intersection between autoimmune thrombophilia and early-onset PE via its effects on endothelial integrity." (PMID 40862707, 2025). "Apolipoprotein H (ApoH, also known as beta-2-glycoprotein I) is a plasma protein involved in antiphospholipid syndrome (APS syndrome)." (PMID 34945690, 2021). "As an example, Q95LB0 APOH_PANTR (protein: Beta-2-glycoprotein 1; gene: APOH) binds to various kinds of negatively charged substances such as heparin, phospholipids, and dextran sulfate in the antiphospholipid syndrome." (PMID 38276668, 2023).
thrombosis (94 papers, 2004 to 2026). "Polymorphisms in the APOH gene that affect these functions, are risk factors for venous thrombosis in a Chinese population." (PMID 32612202, 2020). "In addition, APOH is called β2-Glycoprotein I (β2GPI) and is associated with thrombosis and causes thrombophilia." (PMID 27336623, 2016). "High levels of pathogenic ApoH antibody in turn could cause hypercoagulation and venous and arterial thrombosis, and is clinically relevant to APS." (PMID 22701550, 2012).
lupus (53 papers, 2004 to 2026). "Rs1801690 and another missense SNP, rs1801689 [Cys325Gly, also known as Cys306Gly], were also associated with ApoH levels in lupus patients." (PMID 27030319, 2016).
autoimmune disease (37 papers, 2004 to 2026). A disorder resulting from loss of function or tissue destruction of an organ or multiple organs, arising from humoral or cellular immune responses of the individual to their own tissue constituents. "In addition, some specific autoimmune disease biomarker autoantibody targets such as DNA, H4, Ku80, ApoH and Smith are present." (PMID 23776709, 2013).
COVID-19 (35 papers, 2020 to 2026). A disease caused by infection with severe acute respiratory syndrome coronavirus 2. "The majority of the proteins associated with cholesterol metabolism, including APOC1, APOH, and APOE, were found to be decreased, except for APOA4, which was elevated in COVID-19 patients." (PMID 38672194, 2024). "Also, according to IPA analysis, some of them have been associated with viral infection (APOD, APOH, SERPINA1), severe COVID-19 (APOD, APOH, PCYOX1), or leukocyte migration (APOD, IGHV3-13, IGHV3-23, SERPINA1, IGLC7, IGLV3-21)." (PMID 35397534, 2022). "Although the cholesterol metabolism pathway was significantly downregulated (including APOA2, APOC1, APOH, CETP, and APOA4), the increased levels of PCSK9 and APOB suggested the dysregulation of cholesterol metabolism in severe and critical COVID-19 patients." (PMID 35958562, 2022). "Interestingly, proteins such as apolipoprotein H (APOH), C-type lectin domain family 3 member B (CLEC3B), and heat shock 70kDa protein 5 (HSPA5) also showed opposite trends between COVID-19 patients and CoronaVac immunized subjects." (PMID 35686122, 2022). "Other proteins that could potentially be employed in therapies against COVID-19 but that so far have not been associated with the disease are CD5L, VDBP, A1BG, C4BPA, PGLYRP2, SERPINC1, and APOH." (PMID 37371071, 2023). "In particularwe observed a decrease in the HDL components APOA4 and APOC1 in both COVID-19 non-ICU and ICU/F patients (cluster 3) while APOA2, APOD, APOH, APOM and the HDL-associated PON1 protein appear to be decreased mainly in COVID-19 non-ICU patients (cluster 7)." (PMID 36348270, 2022). "In addition, other proteins that could be employed in therapies against COVID-19 but that so far have not been associated with the disease are CD5L, VDBP, A1BG, C4BPA, PGLYRP2, SERPINC1, and APOH." (PMID 37371071, 2023).
atherosclerosis (34 papers, 2003 to 2026). A disease characterized by the build-up of fatty material and calcium deposition in the arterial wall resulting in partial or complete occlusion of the arterial lumen. "Studies have shown that Apolipoprotein H (Apo H) can inhibit the accumulation of intracellular cholesterol, and low expression of Apo H is associated with elevated blood lipid levels and atherosclerosis." (PMID 35807529, 2022). "The pathogenesis of atherosclerosis is related to plasma lipoprotein metabolism, and ApoH is associated with the atherogenic and thrombotic processes." (PMID 28883884, 2017). "In this study, we conducted a multi-ancestry genome-wide association study (GWAS) of quantitative total anti-β2GPI levels in 5,969 participants enrolled in the Multi-Ethnic Study of Atherosclerosis (MESA) and identified a genome-wide significant association at the APOH locus." (PMID 41867182, 2026). "Large differences in apoB, apoCI, apoCIII,apoF, apoH, and LPa between CKD5 and CVD patients were found, underlining the factthat atherosclerosis in patients with CKD is a different process than that inpatients with classical CVD." (PMID 27600335, 2016). "PCSK9 has similar roles in atherosclerosis development and increases with age as APOH does." (PMID 32587953, 2020). "ApoH may be proatherogenic by promoting an immune response in mice and likely increases the progression of atherosclerosis." (PMID 28883884, 2017).
Arterial thrombosis (22 papers, 2003 to 2026). The formation of a blood clot inside an artery. "Among the most relevant predictors for arterial thrombosis and atherosclerotic cardiovascular diseases are those that target β2-glycoprotein I (β2GPI), a plasma protein encoded by the APOH gene." (PMID 26820623, 2016).
diabetes (14 papers, 2013 to 2025). "For HDL-C, plasma TG, and plasma apoH, such an association with new-onset diabetes did not remain after adjustment for sex, age, BMI, FPG, and HbA1c (model 2)." (PMID 35130909, 2022). "Indeed, several APOH SNPs were nominally associated with diabetes and cognitive performance in the Sydney MAS but not in the smaller OATS cohort." (PMID 27030319, 2016). "Four proteins(14-3-3, ApoH, ZAG, and OTO3) showing diabetes-related variation and also changes in relation to obesity were selected for further validation by western blotting." (PMID 28425473, 2017). "Furthermore, ApoA1 plasma concentration was decreased, whereas ApoC1 and ApoH were increased in the patients with CAD and/or diabetes." (PMID 37686357, 2023).
thrombophilia (13 papers, 2012 to 2026). A condition characterized by an abnormally high level of thrombi. "Even though a mechanistic link between plasma ApoH and cognitive decline has not been established, it may indicate that subclinical hypercoagulation caused by low ApoH might increase the risk of cognitive decline." (PMID 22701550, 2012).
Autoimmunity (9 papers, 2009 to 2024). The occurrence of an immune reaction against the organism's own cells or tissues. "In particular, signature self-antigens such as Smith, ApoH, DNA, histone H4 and phosphatidylserine associated with autoimmunity were present in these ApoBods." (PMID 23776709, 2013). "Male B6.TC/Rab4AQ72L-KO mice were protected from autoimmunity as ANA, anti-ApoH and ACLA production were not increased over B6/Rab4AQ72L-KO controls." (PMID 38519468, 2024).
type 2 diabetes (9 papers, 2014 to 2023). "Plasma ApoH levels are linked to cognitive status, whereas ApoH single nucleotide polymorphisms are associated with type 2 diabetes, chronic inflammatory disease, and age-associated cognitive performance." (PMID 38139244, 2023). "We also found suggestive evidence for associations between APOH SNPs and (i) diabetes type 2 and (ii) cognitive performance." (PMID 27030319, 2016). "We found several of the top APOH SNPs located on chromosome 17 were also nominally associated with diabetes type 2 and cognitive performance in older adults in the full Sydney MAS cohort." (PMID 27030319, 2016). "ApoH regulation may contribute to chronic inflammatory disease, diabetes type 2, and age-related cognitive performance." (PMID 35755170, 2022). "In addition, apolipoprotein H (beta-2-glycoprotein I; Apo H) levels are increased in hyperlipidemic subjects and type 2 diabetics with microalbuminuria." (PMID 30395577, 2018). "This work lays the foundation to improve our understanding of the genetic regulation of ApoH levels and how such variation may contribute to chronic inflammatory disease, diabetes type 2, and age-related cognitive performance." (PMID 27030319, 2016).
breast carcinoma (8 papers, 2009 to 2025). "Among this five-peak panel, three (C3a-desArg, TTR and ApoH) were increased in sera of the breast cancer patients compared to that of HV subjects, while ApoCI and ApoAI were decreased in cancer." (PMID 24935269, 2014). "We observed that levels of ApoAI and ApoCI were significantly downregulated in breast cancer patients, while a peptide identified as a fragment of ApoH was significantly higher in BC." (PMID 24935269, 2014). "APOH, a multifunctional apolipoprotein, has been detected in the sera of breast cancer patients." (PMID 38067270, 2023). "According to the xiantao database, COL1A2, COL3A1, FGA, LUM, APOA1, APOH, and COL5A2 were more highly expressed in breast cancer than in normal tissues (p < 0.05), while the opposite pattern was seen for ALB and FBN1 (p < 0.05)." (PMID 37079213, 2023). "Advanced T-stage breast cancer (T3 and T4) showed increased serum levels of EGF and ApoH, but decreased levels of A1AT." (PMID 19400944, 2009).
Sepsis (8 papers, 2017 to 2026). Sepsis is defined as life-threatening organ dysfunction caused by a dysregulated host response to infection. "Previous research has shown that APOH-deficient mice (APOH−/−) developed earlier onset of severe septicaemia than WT mice (male APOH−/−: 71.4% vs. male WT: 28.6%, with a severity score of ≥ 3) within 24 h following an intravenous injection of E. coli." (PMID 38291524, 2024). "We compared a list of sepsis causing pathogens to the ApoH binding data given to us by ApoH technologies." (PMID 28560277, 2017). "The data highlights the binding of ApoH beads to sepsis causing pathogens." (PMID 28560277, 2017). "This proof-of-concept study demonstrated that APOH has a protective role in the host defense response to sepsis, highlighting the potential therapeutic value of APOH in sepsis treatment." (PMID 38291524, 2024). "In the same way the presence of ApoH has been identified as a protective factor for organ dysfunction and mortality in sepsis." (PMID 39176097, 2024). "In this study, LC–MS/MS was employed to identify potential biomarkers for sepsis in a pilot cohort, and ELISAs were used to confirm the expression of APOH in a validation cohort." (PMID 38291524, 2024). "The expression levels of APOH were subsequently validated in an independent patient cohort, comprising thirty-six sepsis patients and sixty-nine healthy controls." (PMID 38291524, 2024). "Overall, these findings suggest that APOH plays a protective role in sepsis by suppressing M1 polarization, at least partially, by inhibiting of the TLR4/NF-κB signalling pathway." (PMID 38291524, 2024). "To illustrate the variation of APOH expression throughout sepsis progression, we determined the serum levels of APOH in polymicrobial sepsis induced by CLP." (PMID 38291524, 2024). "Secondly, for a more comprehensive understanding of the molecular mechanisms underlying local and systemic inflammation amplification during sepsis, additional research using APOH knockout mice is necessary." (PMID 38291524, 2024). "To further confirm the protective role of APOH in CLP-induced sepsis, we assessed the effects of different doses (5–20 μg) of recombinant murine APOH on severe sepsis in the CLP model." (PMID 38291524, 2024). "On the other hand, ApoH has been shown to exert a protective role in sepsis as a scavenger of lipopolysaccharides in Gram negatives." (PMID 36459524, 2022). "This suggests that targeting APOH could be a promising novel therapeutic approach for sepsis treatment." (PMID 38291524, 2024). "In this study, we investigated the involvement of APOH in sepsis." (PMID 38291524, 2024). "The application of recombinant APOH protein as a therapeutic intervention significantly lowered the mortality rate, mitigated organ injury, and suppressed inflammation in mice with severe sepsis." (PMID 38291524, 2024). "Furthermore, the levels of APOH showed a progressive decrease as sepsis advanced." (PMID 38291524, 2024). "However, the precise role of APOH in the immunopathology of paediatric sepsis remains unclear." (PMID 38291524, 2024). "Moreover, non-survivors with sepsis exhibited decreased expression of APOH compared to survivors in the pilot cohort." (PMID 38291524, 2024).
hepatocellular carcinoma (7 papers, 2021 to 2025). A malignant tumor that arises from hepatocytes. "For example, APOH is notably downregulated in hepatocellular carcinoma, suggesting its potential as a tumor biomarker." (PMID 39399493, 2024). "Previous studies showed that CXCL6 enhances the growth and metastases of ESCC cells both in vitro and in vivo, and the expression of APOH in hepatocellular carcinoma and colorectal cancer was higher than that in adjacent tissues." (PMID 37161430, 2023). "In the study of colorectal cancer (CRC) and hepatocellular carcinoma (HCC), it was found that the expression of APOH in tumor tissues was higher than that in adjacent tissues, and APOH showed a perfect function as a biomarker." (PMID 34177903, 2021). "All of these provide strong evidence that APOC3, APOH, HPX, and FGB can be used as biomarkers for hepatocellular carcinoma." (PMID 35449866, 2022).
metabolic syndrome (7 papers, 2014 to 2025). A cluster of metabolic risk factors for CARDIOVASCULAR DISEASES and TYPE 2 DIABETES MELLITUS. "Additionally, elevated levels of APOH, APOC2, and APOC3 have been linked to clinically apparent arteriosclerosis and components of metabolic syndrome (MetS)." (PMID 38034020, 2023). "Apolipoprotein H (ApoH), also known as β2-glycoprotein I (β2GPI) is a phospholipid-binding plasma protein that is involved in lipid metabolism, angiogenesis and atherogenesis, among others, whereas APOC3 or ApoC-III is an important regulator of triglyceride transport and dyslipidemia." (PMID 34359627, 2021).